IL10 (interleukin 10)
Diseases named in the same sentence as IL10 in open-access papers (continued):
Sharing a sentence is not in itself a finding about the gene and the disease.
tumor (continued). "The presence of IL-10 leads to tumor regression and increase in tumor-specific immunogenicity." (PMID 25056661, 2014). "Additionally, prophylactic and therapeutic administration of Lm-MPFG resulted in significantly reduced number of Tregs in tumors and reduced production of anti-inflammatory cytokines such as TGF-β and IL-10 by the tumor-infiltrating Tregs." (PMID 24860789, 2014). "We determined a clear antitumor effect of IL-12 plasmid DNA against an experimental murine tumor, which was associated with shift to a Th1-type cytokines profile, with expression of IL-2, IL-12 and IFN-γ cytokines and reduced expression of IL-10, IL-4 and TGF-β1 cytokines." (PMID 24808638, 2014). "Both ILT4 and IL-10 positive expression were identified in tumor cell cytoplasm, membrane, or both." (PMID 24762057, 2014). "Above studies collectively indicate the involvement of CIP2A during malignant progression of lung tumors and argue in favor of the fact that IL-10 may aid in promoting tumor aggressiveness via upregulation of CIP2A transcription in lung adenocarcinoma." (PMID 25015035, 2014). "Similarly, tumor cells from patients with advanced lung cancer express some type 2 cytokines such as IL-10 and transforming growth factor-β (TGF-β), while little or no levels of type 1 cytokines such as IL-2 and IFN-gamma were noted." (PMID 24872958, 2014). "Additionally, with production of immunomodulatory IL-10, Th2-immunogloublin IgG4 class-switch recombination is favored over IgE, the former being far less potently tumoricidal, further attenuating anti-tumor responses." (PMID 25101088, 2014). "Therefore, IL-10 favors tumor evasion from immune surveillance via suppressing antigen presentation and T cell activation." (PMID 24585413, 2014). "In contrast, some studies proposed that blockage of IL-10 signaling promote anti-tumor immunity." (PMID 25056661, 2014). "Tumor cells can also secrete IL-10, as can tumor-infiltrating macrophages." (PMID 24901008, 2014). "This study suggests that transient inhibition of IL-10 prior to vaccination could improve responses to cancer vaccines that utilize self-tumor antigens." (PMID 24596571, 2014). "TH2 cytokines, glucocorticoids, and growth factors present in the tumor milieu are all known to induce M2-like macrophages, and tumor-derived IL-10 has specifically been shown to inhibit DC differentiation from monocytic precursors and to promote the development of TAM from these cells." (PMID 23874338, 2013). "Indeed, earlier studies have shown that MB49 cell can promote IL-10 production by host splenocytes and IL-10−/− mice displayed prolonged survival and increased capacities to reject tumour after MB49 injection." (PMID 24142880, 2013). "Serum IL-6 and IL-10 levels may serve as complementary tumor markers and contribute to the differential diagnosis in HCC patients." (PMID 27335826, 2013). "Some lines of evidence suggest that certain factors uniquely produced by tumor cells could facilitate an IL-10-rich environment that ultimately fosters Tr1 cell induction." (PMID 23874336, 2013). "IL-10 promotes tumor malignancy by promoting T cell apoptosis and tumor cell survival." (PMID 23566546, 2013). "To assess the possible roles of these cytokines in the suppressive activity of IMCs in the bone marrow of non-tumor-bearing mice, we added neutralizing antibodies to IL-4, IL-10 and TGFβ1 to cultures of mitogen activated T-cells co-cultured with CD11b+GR-1+ IMC." (PMID 23843936, 2013). "Furthermore, CD4+ T cells isolated from peripheral blood of glioblastoma patient showed marked IL-10 production against tumor cells indicating an enrichment of Tr1 cells within the peripheral CD4+ T cell pool in this patient." (PMID 23874336, 2013). "Thus, the progressive induction of IL-10 in tumor infiltrating cells during tumor growth has been shown to suppress anti-tumor adaptive immune responses." (PMID 23653658, 2013).
tumor (continued). "In fact, an elevated IL-10 expression was seen in tumour patients as well as in pregnant women." (PMID 23950929, 2013). "Moreover, in FCs generated with ethanol-treated tumor cells, IL-10 was lower concentration and HSP90α was higher than those in fusion generated with ethanol-untreated tumors." (PMID 23717436, 2013). "In particular, IL-10 expression by tumor cells correlates with tumor progression." (PMID 24130734, 2013). "Could induced regulatory cells that present in the form of IL-10-producing Tr1 cells be beneficial in the context of tumor immunity?" (PMID 23874336, 2013). "In order to explore the underlying regulatory mechanism(s), sera obtained from control and orlistat-administered tumor-bearing mice were analysed for the level of IL-10, TGF-β and IFN-γ, which are reported to regulate BMC survival and differentiation of macrophage precursors." (PMID 24349275, 2013). "As an immunosuppressive molecule allowing tumor to escape from immune surveillance, IL-10 might act as a potential tumor promoter which results in a more aggressive behavior of malignant cells." (PMID 23460834, 2013). "IL-6 was defined as a crucial factor for tumor survival and immune evasion, i.e., via induced secretion of IL-10 by regulatory T cells, which effectively suppresses adaptive immune responses towards tumor antigens and induces proliferation of immature myeloid cells." (PMID 23616009, 2013). "On the other hand, IL-10 is known to inhibit T helper cell proliferation, hamper dendritic cell maturation, and inhibit T cells co-stimulatory molecules suggesting that IL-10 in ascites may help tumor cells to evade host immunological surveillance." (PMID 24093089, 2013). "The M2 differentiation was also suppressed as evidenced by the lowering IL-10 expression that might favor anti-tumor action." (PMID 24232460, 2013). "To analyze whether CD4, CD25, Foxp3, IL-10, and TGF-β expression in CRC may be associated with clinical tumor progression we investigated tumors of limited disease (UICC I/II) and advanced disease (UICC III/IV)." (PMID 23382847, 2013). "Under both scenarios, IL-10 may influence tumor cells through the development, recruitment, and/or activation of various immune response cells, including tumor-reactive CD8 and other CD4 effector T cell subsets." (PMID 23533029, 2013). "Indeed, IL-10 is suspected to exert both pro- and anti-tumor activities, and contradictory results have been reported regarding its involvement in tumor angiogenesis." (PMID 23967403, 2013). "Interestingly, we found that IL-7, IL-8 and IL-10 all correlated positively with tumor RTL and T/N RTL ratio." (PMID 23383336, 2013). "Multivariate Cox regression was used to explore whether IL-10 haplotype or mRNA levels may independently predict patient's outcome, after adjusting for various parameters including age, gender, smoking status, tumor histology, and cancer stage." (PMID 22848356, 2012). "In addition, IL-6 and IL-10 are promoters of two different immune response pathways, i.e. Th1 and Th2, and allow the evaluation of host immunological response to the tumour." (PMID 23181118, 2012). "Furthermore, IL-10 is able to inhibit dendritic cell-mediated priming of CD8+ T cells abrogating the induction of an anti-tumor CTL response." (PMID 22674057, 2012). "Suppression of anti-tumor immune response by IL-10 may allow the rapid tumor growth observed in MUC1.Tg mice." (PMID 23028615, 2012). "Although up to now the mechanisms of how Tregs inhibit anti-tumor responses and why Tregs accumulate at tumor sites have to be still elucidated, there is evidence for some Treg-associated molecules to be involved in these processes such as TGF-β1 or IL-10." (PMID 22855687, 2012). "Notably, TGF-β1 is strongly expressed in both the tumor and the tumor-draining lymph node, whereas IL-10 expression is more pronounced in the lymph node, suggesting a more complex regulation of IL-10." (PMID 22674057, 2012).
tumor (continued). "Additionally, a contribution to tumour progression in CC, by immunosuppressive cytokines such as IL-10, has been previously suggested." (PMID 22220169, 2012). "Additionally, expression of the immunosuppressive cytokines TGF-β1 and IL-10 became more evident with increased tumor burden." (PMID 22674057, 2012). "The increase of tumour growth by IL-10 could be induced by at least three different simultaneous mechanisms: direct stimulation of cell proliferation through an autocrine mechanism, induction of angiogenesis, and the suppression of the local immune system." (PMID 22220169, 2012). "Additionally, other suppressive factors found in the tumor microenvironment including interleukin-10 (IL-10), transforming growth factor β, prostaglandine E2 (PGE2), and indoleamine 2,3-dioxygenase (IDO), lead to T cell suppression." (PMID 23133545, 2012). "Serum IL-10 was lower (p < 0.0001) in the mice that received DCs exposed to cryotreated tumor lysates with intraperitoneal injection of anti-TGF-β antibody (20.33 ± 9.05 pg/mL) than in the group that received only intraperitoneal injection of anti-TGF-β antibody (103.73 ± 18.37 pg/mL)." (PMID 22415727, 2012). "Nevertheless, data concerning the role of IL-10 for tumor progression are partially inconsistent." (PMID 22855687, 2012). "Moreover, several studies have demonstrated that IL-10 has the physiological role of downregulating cell-mediated immunity, resulting in the improvement of tumour immune escape." (PMID 23181118, 2012). "The biological significance of IL-10 production by tumor cells remains unexplored." (PMID 23148667, 2012). "IL-10, one of the Th2 cytokines, downregulates tumour specific immune responses by directly suppressing IFNc and IL-12 production, thereby reducing major histocompatibility complex expression on the surface of tumour cells and inhibited tumour antigen presentation by antigen presenting cells." (PMID 23131226, 2012). "Factors that are known to promote SCC progression and have been associated with poor prognosis included CCL22, a chemokine that attracts regulatory T cells (Tregs) that shut down the anti-tumor immune response, IL-10, an immuno-regulatory/suppressive cytokine, and IL-4, a prototypical Th2 cytokine." (PMID 22558071, 2012). "It is speculated that production of IL-10 by tumor cells may represent an “escape mechanism” whereby tumor cells avoid Th1-immune-mediated tumoricidal effects." (PMID 22778725, 2012). "IL-10 derived from regulatory T-cells in the tumor or from cells in the tumor microenvironment may stimulate tumor progression." (PMID 22353218, 2012). "The increase in IL-10 and IL-4 release on group P animals may enhance the host immune response against the tumor and aid in the control of tumor growth." (PMID 22827934, 2012). "In fact, CD163+ “tumor-promoting” M2 macrophages which can be abundant in the microenvironment of colorectal carcinomas are activated by cetuximab and in turn they release anti-inflammatory and tumor-promoting mediators, including IL-10 and VEGF." (PMID 23316197, 2012). "In our study, the low levels of IL-10 detected in tumour initiation phase could be contributed to murine SCC development." (PMID 23176085, 2012). "Tumor-associated macrophages play an important role in tumor progression due to production of several angiogenic factors, such as VEGF, IL-8, inflammatory cytokines (IL-1 and IL-10) and proteases (MMP-2 and MMP-9)." (PMID 23024650, 2012). "Particularly in CC, immunosuppression is the main mechanism proposed by which IL-10 could promote tumour growth in human tumours and murine models." (PMID 22220169, 2012). "The number of Treg cells, which produce IL-10, increases in tumor tissues." (PMID 23028615, 2012). "Indeed, immunosuppressive factors, such as VEGF-A and IL-10 released by tumor cells, induce expression of TIM-3 in dendritic cells which results in impaired response to nucleic acid-stimulated tumor immunity." (PMID 23316202, 2012).
tumor (continued). "IL-10 is a multifunctional cytokine with both immunosuppressive and anti-angiogenic functions, and it may have both tumor-promoting and -inhibiting properties." (PMID 23139816, 2012). "High IL-10 expression in tumor- and stromal cell areas of primary tumors predicted mortality." (PMID 22353218, 2012). "Our results also suggest that mycoplasmas infecting tumor cells could utilize tumor-derived exosomes to induce a B cell response and the production of B cell-derived regulatory cytokines IL-10, which could further lead to the inhibition of T cell activity." (PMID 22558358, 2012). "So the role of IL-10 in tumor microenvironment is still controversial." (PMID 22778768, 2012). "To evaluate this hypothesis we have measured the concentration of selected cytokines: TNF, IFNγ, IL-12 (p70), MCP-1, IL-6, and IL-10 in the tumor lysates and in the sera taken from mice at the time of their sacrifice." (PMID 23251384, 2012). "IL-10 has been shown to promote tumor progression via suppressed tumor immune surveillance." (PMID 23118878, 2012). "Evidence suggests that the immune function of microglia might be suppressed when these cells are located inside the tumor, as a result of inflammatory cytokine production, such as interleukin-10 (IL-10), IL-4, IL-6, TGF-β, and prostaglandin E2 by cancer cells." (PMID 22973309, 2012). "However, other cytokines produced by the tumors such as IL-4 and IL-10 are required to induce polarization towards M2 macrophages that facilitates tumor growth, invasion, and angiogenesis." (PMID 23320019, 2012). "The microenvironment rich in IL-10 was likely to promote tumor growth." (PMID 23028615, 2012). "Similarly to the IFNγ/STAT1 signaling, STAT3 and IL-10 can form a positively regulatory loop to promote tumor progression and metastasis through sustaining immunosuppressive environment in tumor tissue." (PMID 21931823, 2011). "The expression of Foxp3 and IL-10 mRNA increased significantly in tumor-bearing mice (P < 0.01)." (PMID 21963624, 2011). "Thus, activation of IL-10/STAT3 can impair autophagy induction and decrease autophagy-associated tumor cell death." (PMID 21931823, 2011). "In this respect, IL-10 has been related to the regulation of MICA expression in tumor cells." (PMID 24212778, 2011). "In addition, blocking of immune suppressive molecules expressed by the tumor or by DC (IL-10, TGFβ, PDL-1) are likely to improve T cell responses." (PMID 24212804, 2011). "M1 macrophages secrete IL-12 and NO, promote antitumor immunity and directly kill tumor cells, whereas alternatively activated M2 macrophages exhibit defective production of IL-12, high IL-10 secretion, produce arginase, suppress the antitumor response and promote angiogenesis and metastasis." (PMID 21633700, 2011). "Besides being produced by T-cells, B-cells, and monocytes, IL-10 has been shown to be produced by BCC tumor cells as well." (PMID 21980389, 2011). "The association might have been stronger if we had been able to differentiate the IL-10 mRNA expressed by immune cells from that made by the tumor cells." (PMID 21980389, 2011). "Overall, these results suggest that it may be possible to improve IL-12 production and decrease IL-10 production to enhance anti-tumor activity of TCL-CMQ." (PMID 21689407, 2011). "Furthermore, anti-inflammatory cytokine (IL-10) expression in EBV+ (positive) samples were characterized to indicate its relevance with viral persistence in tumour cells." (PMID 21791113, 2011). "Since IL-1β has been shown to induce the expression of MCP-1 leading to chronic inflammation, we hypothesized that IL-1β-may induce the expression of MCP-1 and IL-10 in HR tumor cells." (PMID 21978632, 2011). "IL-10-producing NK cells were detected only in WT mice after tumor inoculation (p<0.05)." (PMID 21484786, 2011). "It has been proposed that hypomethylation of the IL-10 gene could be involved in the process of breast carcinogenesis." (PMID 24212778, 2011).
tumor (continued). "Moreover, the inhibition of macrophage infiltration by transfecting IL-10 into Chinese Hamster Ovary cells, suppressed subsequent tumour growth." (PMID 22005011, 2011). "As would be expected, TAMs possess M2-like traits; Tumour cells and the tumour microenvironment release a variety of factors that facilitate this, including IL-4, IL-6, IL-10, PGE2, TGF-β1 and CSF-1, expressed by tumour cells, as well as IL-10, PGE2 and MMP-7 expressed by TAMs." (PMID 22005011, 2011). "Mouse studies suggest a critical role for CSF-1 in attracting monocytes at the tumor site, while cytokine imbalance in favour of IL-10 and TGF-β in the microenvironment could foster immunosuppression and polarize macrophages to elicit pro-tumoral functions." (PMID 22163010, 2011). "However, MHC class IIlow TAMs in the Hepa1-6 tumor model are more likely to mediate suppression of T-cell activation via production of IL-10 and TGF-β." (PMID 21813021, 2011). "Furthermore, the authors found that interleukin-10 and tumor growth factor-β secreted from Tregs are involved in the proliferation of IgG4-positive plasma cells, excess IgG4 secretion, fibrosis and tumor formation." (PMID 21943114, 2011). "The data also suggested that TAMs may involve in tumor immunosuppression through overexpressed IL-10." (PMID 21595995, 2011). "Tumor-associated cytokines such as VEGF, IL-10 and PGE-2 can profoundly affect the nature of APCs." (PMID 21645356, 2011). "Sp1, an important mediator of the cell cycle, may activate IL-10 in response to inflammatory signals and play a role in the cellular responses to DNA damage and tumor metastasis." (PMID 21457566, 2011). "Because tumor cells produce various anti-inflammatory cytokines and growth factors, such as IL-6, IL-10, IL-13, VEGF, and M-CSF, OSCC-derived immunosuppressive cytokines may modulate infiltrating TAMs, leading to the M2 phenotype." (PMID 24213108, 2011). "There are also pre-clinical data suggesting that one mechanism of anti-tumor activity induced by CTLA-4 blockade may be through a decrease in IL-10 secretion." (PMID 24213115, 2011). "As a multifunctional Th2-cytokine with both immunosuppressive and anti-angiogenic functions, interleukin-10 (IL-10) may have both tumor-promoting and tumor-inhibiting properties." (PMID 20553628, 2010). "Due to its immunosuppressive and anti-inflammatory properties, it has been hypothesized that IL-10 contributes to tumor escape from immune surveillance, thereby enhancing tumor growth." (PMID 20735825, 2010). "Besides RNA expression, we also demonstrated IL-10 protein expression in tumor infiltrating macrophages." (PMID 20525400, 2010). "Moreover, transgenic mice expressing IL-10 show accelerated tumor growth that can be diminished by IL-10 neutralizing antibody." (PMID 20525400, 2010). "IL-10 production by tumor associated myeloid cells, mainly macrophages, induces expansion of HPV specific regulatory T cells, possibly inhibiting effector T cell anti-tumor activity." (PMID 20525400, 2010). "The role of IL-10 in colorectal carcinogenesis is complex as it can alternately promote and inhibit carcinogenesis, and both increased and decreased IL-10 gene or protein expression have been found in tumour tissue." (PMID 20924374, 2010). "In addition as cortisol can control the production of IL-10 and TGF-β, these cytokines have been linked to the establishment of immune suppression in the tumor microenvironment by aiding in the expansion of FoxP3+ regulatory T cells (Treg)." (PMID 20946663, 2010). "Due to the described roles of IL-10 in the literature, we raised the hypothesis that IL-10 may be involved in the mechanism by which this macrophage population facilitates tumor growth." (PMID 20525400, 2010). "Furthermore, the suppressor functions of MDSCs and Treg cells are enhanced by IL-17-upregulated IL-10 and IL-13 in tumor microenvironment and CD39 and CD73 on Treg cells." (PMID 20111717, 2010).